ZNF558 (zinc finger protein 558)
Description:
May be involved in transcriptional regulation.
Synonyms: FLJ30932
Tractability: PROTAC: ubiquitination databases record sites on it.
Gene: Protein-coding gene on chromosome 19 (8,806,170 to 8,832,314, reverse strand). Ensembl gene ENSG00000167785.
Subcellular location: Nucleus
Pathways (Reactome):
Gene expression (Transcription): Generic Transcription Pathway
Gene Ontology:
Molecular function: DNA-binding transcription repressor activity, RNA polymerase II-specific; protein binding; DNA-binding transcription factor activity, RNA polymerase II-specific; RNA polymerase II transcription regulatory region sequence-specific DNA binding
Biological process: regulation of transcription by RNA polymerase II; negative regulation of transcription by RNA polymerase II; regulation of DNA-templated transcription
Cellular component: nucleus
Genetic constraint (gnomAD): Loss-of-function variants: 17 observed, 31.25 expected, observed/expected ratio (o/e) 0.54, 90% interval 0.37 to 0.82. The upper end of that interval is the gene's LOEUF score, 0.82, which puts it in group 3 of 6, group 1 being the genes least tolerant of losing a copy. Missense variants: 400 observed, 467.94 expected, observed/expected ratio (o/e) 0.85, 90% interval 0.79 to 0.93. Synonymous variants: 178 observed, 171.06 expected, observed/expected ratio (o/e) 1.04, 90% interval 0.92 to 1.18.
Homologues: Orthologues: chimpanzee ZNF558 (99% identical), macaque ZNF558 (97% identical), guinea pig ZNF558 (88% identical), pig ZNF558 (87% identical), rabbit ZNF558 (86% identical), mouse Zfp558 (80% identical), Drosophila melanogaster CG3281 (29% identical), Drosophila melanogaster CG2712 (27% identical), Drosophila melanogaster Phs (24% identical). Paralogues in human: ZNF557 (78% identical), ZNF891 (49% identical), ZNF805 (47% identical), ZNF778 (47% identical), ZNF264 (46% identical), ZFP37 (45% identical), ZNF266 (44% identical), ZNF555 (44% identical), ZNF77 (44% identical), ZNF19 (43% identical), ZNF554 (43% identical), ZFP90 (43% identical), and 50 more.
Diseases named in the same sentence as ZNF558 in open-access papers:
ZNF558 is named in the same sentence as 4 diseases in open-access papers, as found by Europe PMC text mining. Sharing a sentence is not in itself a finding about the gene and the disease. The quoted sentences say what the papers report.
endometrial cancer (1 paper, 2022). Primary or metastatic malignant neoplasm involving the endometrium (mucous membrane that lines the endometrial cavity). "Interestingly, the expression of ZNF558 and PTGDS was significantly decreased in endometrial cancer in this analysis." (PMID 35163161, 2022). "Moreover, it has also been reported that LGR5, SST, ZNF558, and PTGDS may be involved in the development and progression of endometrial cancer." (PMID 35163161, 2022).
psychiatric disorder (1 paper, 2024). A disorder characterized by behavioral and/or psychological abnormalities, often accompanied by physical symptoms. "Our results suggest that ASTN2 deletion is related to the common pathogenic mechanism of psychiatric disorders by regulating mitophagy via ZNF558." (PMID 38830862, 2024). "Our results suggest that as a pathogenic mechanism for psychiatric disorders, ASTN2 deletion promotes mitophagy by downregulating ZNF558 expression in human neuronal cells." (PMID 38830862, 2024).
ZNF558 also shares sentences with these, for which no sentence is quoted: glioblastoma (1 paper); psoriasis (1).